FCER1A (Fc epsilon receptor Ia)
Description:
High-affinity receptor for immunoglobulin epsilon/IgE. Mediates IgE effector functions in myeloid cells. Upon IgE binding and antigen/allergen cross-linking initiates signaling pathways that lead to myeloid cell activation and differentiation. On mast cells, basophils and eosinophils stimulates the secretion of vasoactive amines, lipid mediators and cytokines that contribute to inflammatory response, tissue remodeling and cytotoxicity against microbes. Triggers the immediate hypersensitivity response to allergens as a host defense mechanism against helminth parasites, pathogenic bacteria and venom toxicity. When dysregulated, it can elicit harmful life-threatening allergic and anaphylactic reactions.
Synonyms: FcERI; FCE1A; FcepsilonRIalpha; FCERIA
Tractability: Small molecule: a structure with a bound ligand is known; it has a binding pocket of medium quality. Antibody: UniProt places it where antibodies can reach, with high confidence; its Gene Ontology location is reachable by antibodies, with high confidence; UniProt predicts a signal peptide or a membrane-spanning region. PROTAC: its protein half-life has been measured.
Target class: Membrane receptor
Gene: Protein-coding gene on chromosome 1 (159,289,714 to 159,308,224, forward strand). Ensembl gene ENSG00000179639.
Subcellular location: Cell membrane
Pathways (Reactome):
Immune System: FCERI mediated Ca+2 mobilization; FCERI mediated MAPK activation; FCERI mediated NF-kB activation; Fc epsilon receptor (FCERI) signaling; Role of LAT2/NTAL/LAB on calcium mobilization
Gene Ontology:
Molecular function: high-affinity IgE receptor activity; IgE binding; protein binding
Biological process: eosinophil degranulation; mast cell degranulation; type 2 immune response; type I hypersensitivity; cell surface receptor signaling pathway; immunoglobulin mediated immune response; Fc-epsilon receptor signaling pathway
Cellular component: cell surface; plasma membrane; external side of plasma membrane
Genetic constraint (gnomAD): Loss-of-function variants: 18 observed, 18.72 expected, observed/expected ratio (o/e) 0.96, 90% interval 0.66 to 1.42. The upper end of that interval is the gene's LOEUF score, 1.42, which puts it in group 5 of 6, group 1 being the genes least tolerant of losing a copy. Missense variants: 254 observed, 252.19 expected, observed/expected ratio (o/e) 1.01, 90% interval 0.91 to 1.12. Synonymous variants: 101 observed, 96.34 expected, observed/expected ratio (o/e) 1.05, 90% interval 0.89 to 1.24.
Homologues: Orthologues: chimpanzee FCER1A (99% identical), macaque FCER1A (92% identical), rabbit FCER1A (61% identical), pig FCER1A (59% identical), dog FCER1A (53% identical), mouse Fcer1a (47% identical), rat Fcer1a (45% identical). Paralogues in human: FCGR3A (35% identical), FCGR3B (34% identical), FCGR1A (33% identical), FCGR2B (33% identical), FCGR2C (33% identical), FCRLB (31% identical), FCGR2A (31% identical), FCRL5 (29% identical), FCRL4 (28% identical), FCRL3 (27% identical), FCRLA (22% identical), FCRL6 (18% identical), and 5 more.
Diseases named in the same sentence as FCER1A in open-access papers:
FCER1A is named in the same sentence as 70 diseases in open-access papers, as found by Europe PMC text mining. Sharing a sentence is not in itself a finding about the gene and the disease. The quoted sentences say what the papers report.
asthma (25 papers, 2008 to 2025). "Genetic polymorphisms of the FCER1A gene may affect IgE levels related to asthma." (PMID 40672946, 2025). "Analysis of asthmatic GWAS showed differential inflammatory genes (e.g., HLA-DPB1, HLA-DQA1, FCER1A), which verified the inflammation levels of asthma model." (PMID 36439114, 2022). "FCER1A is involved in inducing the inflammatory and immediate hypersensitivity responses in allergic disorders such as hay fever, asthma, and chronic idiopathic urticaria." (PMID 23515576, 2013). "In addition to many important asthma-related genes identified in the current study, basophil-specific gene signatures, such as Mcpt8, Ms4a2, Cpa3, Fcer1a, and Cd200r3 were highly expressed in the AM group." (PMID 40443683, 2025). "In the KEGG analysis, the item of ‘Asthma’ (FDR = 1.28E-06) was significantly enriched and the down-regulated FCER1A was enriched in this pathway." (PMID 33419394, 2021). "Many other pathways were also identified that are regulated by IL-13 and relevant to asthma pathogenesis (e.g. CCL17, CCL26, CTGF, FCER1A, KITLG, MUC2, NOS2, TLR3)." (PMID 29367592, 2018). "The expression levels of FCER1A and TLR‐9 in IL‐5‐ or IL‐17‐activated eosinophils and those of aryl hydrocarbon receptor and TLR‐7 in IL‐5‐activated eosinophils were significantly higher for patients with asthma than for normal individuals." (PMID 39575691, 2024). "The expression levels of IL17RA, IL4RA, integrin β2, CCR3, FCER1A, TGFB1, TLR‐3, TLR‐7, and TLR‐9 in eosinophils treated with IL‐17 for 3 h were higher for normal individuals than for patients with asthma." (PMID 39575691, 2024).
Allergy (21 papers, 2012 to 2025). An allergy is an immune response or reaction to substances that are usually not harmful. "The relationship between FCER1A gene variants and allergic diseases has been demonstrated in human studies." (PMID 34566889, 2021). "The structure and function of the FcεR1A gene, encoding for α-subunit of FcεRI (FcεRIα), plays an important role in the pathogenesis of allergic diseases." (PMID 25923080, 2015). "However, in the context of infectious pneumonia—a prototypical hyperinflammatory disorder under investigation in this study—we consistently observed a significant downregulation of FCER1A, a gene intricately associated with allergy and immune regulation." (PMID 41300746, 2025). "The mutations of FCER1A have been reported in multiple human allergic disease studies." (PMID 36430822, 2022). "FCER1A codes for the alpha subunit of IgE receptor associated with allergy response." (PMID 34335605, 2021). "Some studies have hypothesized about the possible mechanisms underlying the association between the FCER1A gene and breast cancer, and suggested that immune-stimulating conditions such as infectious diseases and allergies may actually confer susceptibility to breast cancer." (PMID 34566889, 2021). "FCER1A (Fc fragment of IgE receptor Ia, FCER1A), an immune-related protein, is the initiating factor of allergic reactions and plays a role in allergic inflammation." (PMID 36823620, 2023). "FCER1A (Fc fragment of IgE receptor Ia) is an IgE receptor (immunoglobulin receptor), which is the initiating factor of allergic reactions and plays a role in allergic inflammation." (PMID 35045818, 2022). "Studies looking into FCER1A in the respiratory system mainly focus on mast cell and basophils, two major cells involved in allergy." (PMID 34457122, 2021). "Peanut-induced allergic reactions resulted in a significant decrease in circulating basophil counts compared with those in prechallenge samples (P = .016), a decrease in FCER1A expression (P = .007), and an increase in CCL2 levels (P = .003)." (PMID 28342911, 2017). "Furthermore, a two-sample MR approach leveraging large GWAS and eQTL databases suggested a potential causal role for IL4, IL1RL1, RP11-13A1.1, FCER1A and MS4A2, RUNX1, and ACLS6 expression in various allergic diseases and serum IgE levels." (PMID 36725846, 2023). "Indeed, a Mendelian randomization approach based on GWAS summary statistics indicates that several of these genes, including interleukin-4 (IL4) and IgE receptors (FCER1A, MS4A2), affect the incidence of allergic diseases." (PMID 36725846, 2023).
anaphylaxis (7 papers, 2017 to 2024). An acute hypersensitivity reaction that occurs from exposure to an allergen. "We then studied passive cutaneous anaphylaxis reaction (PCA), the pathology of which solely relies on the presence of FcεRIα, in wild-type, homozygous FCER1Adtr/dtr, and FCER1A-KO mice." (PMID 37154775, 2023).
allergic rhinitis (6 papers, 2010 to 2025). Inflammation of the nasal mucous membranes caused by an IgE-mediated response to external allergens. "Our study aimed to evaluate the contribution of single nucleotide polymorphisms (SNPs) in the FCER1A gene region to allergic rhinitis (AR) susceptibility in a Chinese population-based case-control association analysis." (PMID 21209833, 2010). "The aim of this study was to investigate whether the polymorphisms in the FCER1A gene are associated with allergic rhinitis (AR) in a Han Chinese population." (PMID 21209833, 2010).
COVID-19 (6 papers, 2021 to 2025). A disease caused by infection with severe acute respiratory syndrome coronavirus 2. "•PPI-identified hub genes IL7R/CD2/GZMA/CD3D/FCER1A diagnose COVID-19 and diabetic nephropathy with AUC>0.80, linking immune activation to tissue damage." (PMID 41332907, 2025). "In a parallel analysis, the datasets from GSE152418 revealed pronounced differences in the expression of IL7R, CD2, CD3D and FCER1A when comparing COVID-19 samples to control samples." (PMID 41332907, 2025). "In lung, CD40, CD80, CD83 and HLA-DQA2 were upregulated while CD86 and FCER1A were decreased in mild COVID-19 as compared to healthy controls." (PMID 34502134, 2021). "For COVID-19, the AUCs of IL7R, CD2, GZMA, CD3D, and FCER1A were 0.925, 0.934, 0.905, 0.950, and 0.998, respectively." (PMID 41332907, 2025). "The expression of cell-specific genes such as FCER1A in monocyte-derived dendritic cells, PPBP in megakaryocyte, ITGB3 in NK cells, and PF4 in T cells of COVID-19 patients was obviously lower than that in healthy controls." (PMID 36403042, 2022). "Compared to mild cases, severe COVID-19 showed upregulated CD40 together with downregulated CD83, HLA-DQA2 and FCER1A in all three tissues." (PMID 34502134, 2021). "The dysregulation of DC function in COVID-19 was also presented by the expression of the maturation marker (CD83), T-cell stimulation molecules (CD40, CD80, CD86) and antigen presentation molecules (HLA-DQA2 and FCER1A)." (PMID 34502134, 2021). "But the decreased level of FCER1A in COVID-19 patients seemed to not explain the potential role of the activation of mast cell or that basophil plays in hyperinflammation with patients, which deserves to be further studied." (PMID 34457122, 2021). "In contrast, the expression of FCER1A, HLA-DMB, and CD1C was not different between severe COVID-19 and non-COVID-19 patients." (PMID 38262689, 2024).
Sepsis (5 papers, 2018 to 2025). Sepsis is defined as life-threatening organ dysfunction caused by a dysregulated host response to infection. "CCR3, PTGDR2 (alias CRTH2), and FCER1A are associated with allergic processes and have been described in sepsis and bacterial meningitis." (PMID 30463588, 2018). "In the present study, FCER1A was determined as a hub gene to the predict prognosis of sepsis, which was consistent with a previous study showing that FCER1A was identified as a potential diagnostic biomarker for sepsis." (PMID 37180171, 2023). "In the present study, we identified 5 lipid metabolism-related hub genes (MAPK14, EPHX2, BMX, FCER1A, and PAFAH2) that have the possibility of diagnostic and therapeutic in patients with sepsis by machine learning analysis." (PMID 37180171, 2023). "In a previous study, we evidenced that FCER1A (Fc Fragment Of IgE Receptor Ia) is the gene showing the lowest expression levels of the entire transcriptome in sepsis." (PMID 30890150, 2019). "Innate immunity and inflammation, such as ZDHCC19, ALOX15, FCER1A, HDC, PRSS33, and PCSK9, were upregulated in elderly ICU patients with sepsis." (PMID 36823620, 2023). "On day-8 in elderly ICU patients with sepsis, genes related to innate immunity and inflammation, such as ZDHCC19, ALOX15, FCER1A, HDC, PRSS33, and PCSK9, were upregulated." (PMID 36823620, 2023).
urticaria (4 papers, 2010 to 2024). A vascular reaction of the skin characterized by erythema and wheal formation due to localized increase of vascular permeability. "In both cases, the allele associated with increased FCER1A RNA levels in blood is also associated with decreased risk of urticaria, like rs6703348[G]." (PMID 37430141, 2023). "In the Icelandic data, the urticaria-associated variant rs6703348[G] at FCER1A is highly correlated with two top eQTLs for RNA levels of FCER1A in blood and in monocytes (r2 = 0.98 and 0.82, respectively)." (PMID 37430141, 2023). "For variants at the FCER1A and the STAT6 loci, the allele that associates with lower risk of urticaria also associates with decreased serum IgE levels and both are highly correlated with variants previously reported to associate with serum IgE levels (r2 of 0.87 and 1.00, respectively) 20,21." (PMID 37430141, 2023).
atherosclerosis (3 papers, 2019 to 2024). A disease characterized by the build-up of fatty material and calcium deposition in the arterial wall resulting in partial or complete occlusion of the arterial lumen. "Among major findings, our results suggest a role of triglyceride-associated and mast-cell functional genes FCER1A, MS4A2, GATA2, HDC, and HRH4 in atherosclerosis risks." (PMID 39276247, 2024). "C0 C1QC+ macrophages, C2 FCN1+ macrophages, and C4 FCER1A+ macrophages had high chromosome copy number variation, which may be related to the progression of atherosclerosis." (PMID 39726810, 2024). "Homozygous deletion of FCER1A reduced atherosclerosis in Apoe–/– mice." (PMID 39276247, 2024). "FCER1A and HDC have also been experimentally linked to atherosclerosis." (PMID 39276247, 2024).
autoimmune disease (3 papers, 2022 to 2025). A disorder resulting from loss of function or tissue destruction of an organ or multiple organs, arising from humoral or cellular immune responses of the individual to their own tissue constituents. "Moreover, FCER1A exhibits dysregulated expression in autoimmune diseases like systemic lupus erythematosus and specific cancers (e.g., breast and lung cancers), suggesting its broader role in immune regulation." (PMID 41300746, 2025).
breast carcinoma (3 papers, 2020 to 2022). "Two significant genes (CD1a and FCER1A) related with the survival outcome in the pCR prediction model have been reported as conventional dendritic cell markers and are highly expressed in innate antigen-presenting cells infiltrating breast cancer tissues, which is consistent with our findings." (PMID 33138797, 2020). "In our study, FCER1A expression was higher in breast cancer samples of nonobese patients than of obese patients." (PMID 34566889, 2021).
viral infection (3 papers, 2020 to 2022). "Furthermore, FCER1A encodes a subunit of the immunoglobulin (Ig) E receptor and is thought to be involved in the immune response to viral infections." (PMID 36543117, 2022). "The 8-gene signature included three genes over-expressed in bacterial infections (SMARCD3, ICAM1, EBI3; “bacterial genes”) and five over-expressed in viral infections (JUP, SUCLG2, IFI27, FCER1A, HESX1; “viral genes”)." (PMID 36543117, 2022).
bacterial sepsis (2 papers, 2021 to 2023). "For example, ALOX15 and FCER1A were monocyte-associated genes, which have been found to play a pivotal role in the pathogenesis of bacterial sepsis." (PMID 34977060, 2021). "Recent research has demonstrated that ALOX15 and FCER1A are crucial to the pathogenesis of bacterial sepsis." (PMID 36823620, 2023).
lung fibrosis (2 papers, 2019 to 2023). "We found that mRNAs encoding LOYBOY, DEEZOY, and SNEYSPORBY were upregulated, and those encoding CPA3, FCER1A, and CCR5 were downregulated; these mRNAs may be involved in silica-induced lung fibrosis." (PMID 30756084, 2019).
sensitization (2 papers, 2008 to 2014). "SNPs in or near JAK2, CNOT6, MAML1, CD40, IL-4R, and IL-5RA genes were associated with allergic sensitization and SNPs in or near JAK1, JAK3, IL5RA, FCER1A, and ADAM33 genes were associated with cockroach sensitization." (PMID 25505553, 2014).
depression (1 paper, 2026). "Our results displayed that the mRNA levels of Fcer1g, Fcer1a, and Fcgr4 were all upregulated in the brains of LPS‐induced depression model mice, which were all down‐regulated by DSCG administration." (PMID 41556446, 2026).
diabetic nephropathy (1 paper, 2025). "The expression levels of IL7R, CD2, GZMA, CD3D and FCER1A significantly differed between diabetic nephropathy and controls." (PMID 41332907, 2025).
gastric tumors (1 paper, 2022). "To shed light on myeloid populations present in gastric tumors, we re-clustered the 10,546 myeloid cells in our dataset and identified fifteen subclusters which were subsequently determined to be either macrophages (CD68, CD14), dendritic cells (FLT3, FCER1A), or neutrophils (CSF3R)." (PMID 36550535, 2022).
leukoplakia (1 paper, 2024). A white patch or plaque on a mucous membrane that cannot be characterized clinically or pathologically as any other disease. "During the progression from leukoplakia to HNSCC, we found several prognostic cell subgroups, such as AURKB + epithelial cells, SFRP1 + fibroblasts, SLC7A8 + macrophages, FCER1A + CD1C + dendritic cells, and TRGC2 + NK/T cells." (PMID 38582791, 2024).
melanoma (1 paper, 2022). A malignant, usually aggressive tumor composed of atypical, neoplastic melanocytes. "While RPMI-7951 melanoma cell supernatant reduced 2.65 times FCER1A expression in MCs in vitro and in vivo, in MAMCs, the expression of FCER1A was reduced by 16 times." (PMID 35669782, 2022).
muscle tumors (1 paper, 2023). "In addition, 25 DPs are related to muscle tumors; 8 DPs (APOE, FCER1A, FCER2, GSK3B, HSPD1, IL6R, MMP7, and RARRES2) are linked to proliferation of muscle cells." (PMID 36918772, 2023).
osteoarthritis (1 paper, 2019). A noninflammatory degenerative joint disease occurring chiefly in older persons, characterized by degeneration of the articular cartilage, hypertrophy of bone at the margins and changes in the synovial membrane. "To further define a role for FcεRI in the pathogenesis of osteoarthritis, we performed DMM surgeries in mice deficient in FcεRIα (Fcer1a-/-)." (PMID 31084709, 2019).
pneumonia (1 paper, 2025). An acute, acute and chronic, or chronic inflammation focally or diffusely affecting the lung parenchyma, caused by an infection in one or both of the lungs (by bacteria, viruses, fungi, or mycoplasma.). "Immunofluorescence staining demonstrated that Fcer1a protein expression and distribution in lung tissues were significantly higher in the normal group than in the pneumonia group, consistent with expectations." (PMID 41300746, 2025). "Subsequently, we established a Pseudomonas aeruginosa-induced pneumonia model in BALB/c mice to validate the expression of the core gene, Fc epsilon receptor Ia (FCER1A), and to analyze its associated pathological, inflammatory, and immunological alterations." (PMID 41300746, 2025). "Animal experiments confirmed pronounced reduction of Fcer1a transcription in both lung tissue and whole blood of pneumonia model mice." (PMID 41300746, 2025). "Immune infiltration analysis in this study demonstrated a significant increase in the infiltration levels of these two cell populations in the lung tissue of the mouse pneumonia model, both of which exhibited a significant negative correlation with FCER1A expression (p < 0.01)." (PMID 41300746, 2025).